GNGT2 (G protein subunit gamma transducin 2)
Description:
Guanine nucleotide-binding proteins (G proteins) are involved as a modulator or transducer in various transmembrane signaling systems. The beta and gamma chains are required for the GTPase activity, for replacement of GDP by GTP, and for G protein-effector interaction.
Synonyms: GNG9; GNGT8; G-GAMMA-8; G-GAMMA-C; HG3I
Tractability: Antibody: UniProt places it where antibodies can reach, with high confidence; its Gene Ontology location is reachable by antibodies, with medium confidence. PROTAC: ubiquitination databases record sites on it.
Gene: Protein-coding gene on chromosome 17 (49,202,791 to 49,210,593, reverse strand). Ensembl gene ENSG00000167083.
Subcellular location: Cell membrane
Pathways (Reactome):
Signal Transduction: Ca2+ pathway; Extra-nuclear estrogen signaling; G alpha (12/13) signalling events; G alpha (i) signalling events; G alpha (q) signalling events; G alpha (s) signalling events; G alpha (z) signalling events; G beta:gamma signalling through BTK; G beta:gamma signalling through CDC42; G beta:gamma signalling through PI3Kgamma; G beta:gamma signalling through PLC beta; G-protein activation; GPER1 signaling; Glucagon-type ligand receptors
Hemostasis: ADP signalling through P2Y purinoceptor 1; ADP signalling through P2Y purinoceptor 12; Prostacyclin signalling through prostacyclin receptor; Thrombin signalling through proteinase activated receptors (PARs); Thromboxane signalling through TP receptor
Neuronal System: Activation of G protein gated Potassium channels; Inhibition of voltage gated Ca2+ channels via Gbeta/gamma subunits; Presynaptic function of Kainate receptors
Metabolism: Adrenaline,noradrenaline inhibits insulin secretion; Glucagon-like Peptide-1 (GLP1) regulates insulin secretion
Cellular responses to stimuli: High laminar flow shear stress activates signaling by PIEZO1 and PECAM1:CDH5:KDR in endothelial cells
Disease: ADORA2B mediated anti-inflammatory cytokines production
Metabolism of proteins: Cooperation of PDCL (PhLP1) and TRiC/CCT in G-protein beta folding
Transport of small molecules: Vasopressin regulates renal water homeostasis via Aquaporins
Gene Ontology:
Molecular function: GTPase activity; G-protein beta-subunit binding
Biological process: G protein-coupled receptor signaling pathway; phototransduction
Cellular component: heterotrimeric G-protein complex; plasma membrane
Genetic constraint (gnomAD): Loss-of-function variants: 4 observed, 5.18 expected, observed/expected ratio (o/e) 0.77, 90% interval 0.38 to 1.65. That is too few expected variants to judge how well the gene tolerates losing a copy. Missense variants: 61 observed, 82.66 expected, observed/expected ratio (o/e) 0.74, 90% interval 0.6 to 0.91. Synonymous variants: 31 observed, 30.03 expected, observed/expected ratio (o/e) 1.03, 90% interval 0.77 to 1.39.
Homologues: Orthologues: chimpanzee GNGT2 (94% identical), rat Gngt2 (84% identical), mouse Gngt2 (83% identical), rabbit GNGT2 (83% identical), guinea pig GNGT2 (77% identical), tropical clawed frog gngt2.1 (71% identical), zebrafish gngt2a (70% identical), tropical clawed frog gngt2 (67% identical), zebrafish gngt2b (55% identical), Drosophila melanogaster Ggamma1 (30% identical). Paralogues in human: GNG11 (64% identical), GNGT1 (64% identical), GNG2 (41% identical), GNG7 (39% identical), GNG3 (38% identical), GNG10 (35% identical), GNG12 (35% identical), GNG4 (33% identical), GNG8 (33% identical), GNG5 (29% identical), GNG5B (28% identical).
Diseases named in the same sentence as GNGT2 in open-access papers:
GNGT2 is named in the same sentence as 17 diseases in open-access papers, as found by Europe PMC text mining. Sharing a sentence is not in itself a finding about the gene and the disease. The quoted sentences say what the papers report.
asthma (5 papers, 2020 to 2024). "Several studies have identified Gngt2 as a risk gene associated with moderate to severe asthma, but its role in severe asthma is unclear." (PMID 39417697, 2024). "Ferreira and coworkers documented that the GNGT2 gene was predicted targets of a sentinel risk SNP of rs12952581 for asthma." (PMID 33066754, 2020). "In addition, GNGT2 gene contains some suggestive asthma-associated SNPs; e.g. rs648980 (PGWAS = 1.93 × 10− 4), rs617182 (PGWAS = 1.95 × 10− 4), rs55978930 (PGWAS = 2.79 × 10− 4), rs113201977 (PGWAS = 4.14 × 10− 4)." (PMID 33066754, 2020). "Thirty‐five hub genes were identified, in which G protein subunit gamma transduction protein 2 (Gngt2) in CD11b+ DCs exhibited a relatively specific increase in expression associated with autophagy defects under the induction environment similar to T2 low asthma model." (PMID 39417697, 2024). "In our study, we illustrate a potential mechanism involving Gngt2 in DC‐mediated autophagy‐axis as a potential therapeutic intervention for T2‐low asthma." (PMID 39417697, 2024). "To better understand Gngt2 expression in asthma model, we conducted further analysis on lung Gngt2 expression using the GSE6858, GSE2276, GSE55247 data sets." (PMID 39417697, 2024). "With the use of a series of bioinformatics analyses, we highlighted 11 important genes such as GNGT2, TLR6, and TTC19 as authentic risk genes associated with moderate-to-severe/severe asthma." (PMID 33066754, 2020). "There were 8 of 11 genes (8/11 = 72.7%) showing significantly different expression profiles between severe asthma and controls; for example, GNGT2, TLR6, TTC19, LNPEP, SLC22A5 and HLA-DQA1." (PMID 33066754, 2020). "We illustrate a novel mechanism involving Gngt2 in DC‐mediated autophagy‐axis in T2‐low asthma." (PMID 39417697, 2024). "Finally, we confirm that the modulatory effects of Gngt2 signaling on Th2/17 differentiation in asthma endotypes depend on autophagy." (PMID 39417697, 2024). "Second, we verify the effects of Gngt2 intervention on autophagy and asthma endotypes." (PMID 39417697, 2024). "In summary, current study provides several lines of evidence to support that 11 highlighted genes including GNGT2, TLR6, and TTC19 could be treated as genuine moderate-to-severe/severe asthma-associated genes." (PMID 33066754, 2020). "In addition, GNGT2 is significantly expressed in severe asthma compared with mild-moderate asthma (P = 0.045), and Gngt2 shows significantly distinct expression patterns between vehicle and various glucocorticoids (Anova P = 1.55 × 10− 6)." (PMID 33066754, 2020). "An intergenic signal between PHB and ZNF652 (rs2584662) (EAF, 0.42; OR, 0.92; P = 2.21 × 10–8) was previously associated with asthma and reported as a blood eQTL for GNGT2 (implicated in NF-κB activation), although we did not identify this in our eQTL analysis." (PMID 35104449, 2022). "First, we observe the changes in Gngt2 and downstream autophagy in DCs using OVA‐induced T2‐high and OVA‐LPS‐induced T2‐low asthma models." (PMID 39417697, 2024). "Our analysis suggested Gngt2 acted as an adapter molecule that inhibited autophagy, promoting Th17‐mediated airway inflammation via the GPCR pathway in a T2 low asthma mice model." (PMID 39417697, 2024).
esophageal cancer (3 papers, 2020 to 2024). A primary or metastatic malignant neoplasm involving the esophagus. "A recent study showed that GNGT2 was closely associated with the survival of esophageal cancer, and serve as a potentially prognostic marker of patients with esophageal cancer." (PMID 35675043, 2022). "In addition, GNGT2 was identified as a potential prognostic marker in esophageal cancer and a hub gene in lung cancer." (PMID 39695086, 2024). "Further, survival analysis showed that GNGT2 was closely related to survival of esophageal cancer." (PMID 32068233, 2020).
colitis (1 paper, 2024). Inflammation of the colon. "Neut-c4, also prevalent in the early colitis phase, expressed genes associated with phagocytosis and reactive oxygen species (ROS) generation (Gngt2, Ltc4s, Gpr84)." (PMID 38674054, 2024).
glioblastoma (1 paper, 2024). The most malignant astrocytic tumor (WHO grade IV). "Retina and anterior neural fold homeobox 2 (RAX2), TUB like protein 1 (TULP1) and G protein subunit gamma transducin 2 (GNGT2) are associated with photoreceptor cells, with TULP1 being involved in retinitis pigmentosa and RAX2 playing a role in the malignant progression of glioblastoma." (PMID 39695086, 2024).
Stroke (1 paper, 2025). Sudden impairment of blood flow to a part of the brain due to occlusion or rupture of an artery to the brain. "Along with Fos and Jun, Cebpb, Ets2, Egr1, and Junb were enriched in Neut_Gngt2 and Neut_Cd14, particularly after stroke." (PMID 39930981, 2025).
tumor (3 papers, 2020 to 2024). "A previous study has indicated that Gngt2 deficiency can promote cell proliferation in tumor cells by upregulating Bcl‐2 expression." (PMID 39417697, 2024).
cancer (2 papers, 2020). A tumor composed of atypical neoplastic, often pleomorphic cells that invade other tissues. "GNGT2 encodes a transducin that may be involved in many cancer-related pathways such as the “chemokine signaling pathway” and “PI3K-Akt signaling pathway”." (PMID 33087120, 2020). "We can speculate that the differential expression of GNGT2 may be involved in the development of cancer." (PMID 32068233, 2020). "According to these well-established functions of EI24, GNGT2 and MIR21, PanDM’s identification of their DM status in cancers is highly likely to reflect a biological reality." (PMID 33087120, 2020).
GNGT2 also shares sentences with these, for which no sentence is quoted: lung carcinoma (2 papers); retinoblastoma (2); Gliosis (1); infection (1); lymphoma (1); myopia (1); Obesity (1); retinitis pigmentosa (1); tauopathy (1); virus infection (1).